LAG3 (lymphocyte activating 3)
Diseases named in the same sentence as LAG3 in open-access papers (continued):
Sharing a sentence is not in itself a finding about the gene and the disease.
Sepsis (35 papers, 2012 to 2026). Sepsis is defined as life-threatening organ dysfunction caused by a dysregulated host response to infection. "The expression of inhibitory receptors such as PD-1, cytotoxic T-lymphocyte–associated protein 4 (CTLA-4), and LAG-3 is significantly increased on CD8+ T cells from sepsis patients." (PMID 41462924, 2025). "Genetic variation in LAG-3 is associated with altered disease severity and outcome in patients with sepsis, and 28-day mortality is significantly lower in LAG-3 rs951818 AA-homozygote patients than in C allele carriers." (PMID 38114466, 2023). "As a main result, our study revealed that LAG-3 rs951818 AA-homozygote patients had a significantly lower 28-day mortality in sepsis compared to carriers of the C-allele (17.3% vs. 23.7%, p = 0.0476)." (PMID 34830585, 2021). "The authors believe that further investigation of the LAG-3 rs951818 function and the underlying biological mechanisms holds significant potential for a better understanding of the multi-faceted syndrome of sepsis." (PMID 34830585, 2021). "LAG-3 knockout or anti–LAG-3 antibody blockade protected mice undergoing CLP from sepsis-associated immune dysfunction and maybe a new target for the treatment." (PMID 38114466, 2023). "Furthermore, treatment with anti-LAG-3 antibody improved the ability to clear primary infections, reduced the incidence of secondary nosocomial infections caused by opportunistic pathogens, and thereby improved survival after sepsis." (PMID 34830585, 2021). "Research indicates that LAG-3 and PD-1 are co-upregulated on T cells from sepsis patients, and they act synergistically to inhibit CD8+ T cell function." (PMID 41462924, 2025). "Given the prominence of LAG-3 expression during late-stage sepsis immunosuppression, blocking this pathway with LAG-3 antibodies is proposed as a potential approach to reverse the immunosuppressive state." (PMID 40806563, 2025). "Beyond the PD-1/PD-L1 axis, other immune checkpoint molecules such as LAG-3 also contribute to T cell suppression in sepsis." (PMID 41462924, 2025). "Lymphocyte activation gene 3 (LAG-3) is an immunoregulatory cell surface protein that negatively regulates T cell proliferation, activation, and homeostasis and is highly expressed in sepsis." (PMID 38114466, 2023). "Lymphocyte activation gene 3 (LAG3) and PD-1 have a potential synergistic effect in regulating the progressive depletion of T cells in sepsis." (PMID 38193090, 2023). "We re-examined the response to ICI treatment in sepsis using PANscore and found that PD-1 was more expressed in the LowPANscore subgroup, while PD-L1, LAG3, TIGIT, TNFRSF9, CD40, IDO1 were expressed in the HighPANscore subgroup (P<0.05)." (PMID 38239341, 2023). "We analyzed the immune targets of immune-related drugs to predict their potential use in sepsis and showed that nine target loci (CSF2RA/B, CSF3R, IFNGR1/2, IL7R, PDL1, CTLA4, and LAG3) differed in the high-/low-risk block." (PMID 36389695, 2022). "Immune checkpoint inhibitors, such as anti-PD1, anti-PDL1, anti-CTLA4, anti-TIM3 and anti-LAG3 antibodies have also been considered as promising therapies in patients with sepsis." (PMID 36279072, 2022). "Upregulated levels of the inhibitory immune checkpoint molecule LAG-3 were previously observed in a cecal ligation puncture (CLP) model of murine sepsis." (PMID 34830585, 2021). "When used in too late stages, the activation of LAG3 will certainly affect the effect of the anti-PD-1 therapy, not only in sepsis but also in cancer." (PMID 31440257, 2019). "- In sepsis, LAG3 and PD-1 had unique expression characteristics in T cells, and the T cells that coexpress LAG3 and PD-1 were significantly exhausted." (PMID 31440257, 2019). "A recent study revealed LAG3 can resist the therapeutic effect of PD-1 blockade in tumor, which inspired us to understand their role in sepsis." (PMID 31440257, 2019).
Sepsis (continued). "By immunofluorescence, the expression of LAG3 and PD-1 on the surface of T cells on the 5th day of sepsis was also directly observed." (PMID 31440257, 2019). "Here, we performed a prospective observational study and systematically analyzed the expression characteristics and functions of LAG3 and PD-1 in T cells as well as the relationship between LAG3 and PD-1 and the prognosis of patients with sepsis." (PMID 31440257, 2019). "Cytotoxic T-cell signaling (CD8A, CD8B) and T-cell inhibitory signaling (LAG3) were overexpressed in HIV patients both during sepsis and in asymptomatic HIV infection." (PMID 26871709, 2016). "In HIV positive sepsis patients their levels were similar, or downregulated to a lesser extent, except for LAG3, which was elevated in HIV positive sepsis patients compared to healthy controls." (PMID 26871709, 2016). "Collectively, current evidence indicates that TIM-3 primarily functions through Tregs to limit excessive inflammation during sepsis, whereas CTLA-4, LAG-3, and TIGIT are more strongly associated with the immunosuppressive state that emerges in the later stages of the disease." (PMID 40806563, 2025). "LAG‐3 and PD‐1 were elevated in clusters enriched in both septic and non‐sepsis patients." (PMID 40041474, 2025). "Patient risk stratification according to genetic profiles and individualized immunotherapies with immune cell checkpoint inhibitors, whether anti-LAG-3 or a combination with others, are surely a future component of sepsis therapy." (PMID 34830585, 2021). "The immune checkpoints such as CTLA-4, PD-1/PD-L1, TIM-3, and LAG-3 are all found to be upregulated on T cells in murine sepsis models, and these coinhibitory molecules have emerged as fundamental targets for reversing sepsis-induced immunosuppression." (PMID 34366711, 2021). "Patient-individual therapeutic targeting of immune checkpoints, such as LAG-3, may be a future component of sepsis therapy." (PMID 34830585, 2021). "Interestingly, this study showed that LAG-3 was only significantly elevated at day 5 post sepsis, as compared to PD-1 which was elevated early at 12 h after sepsis, indicating an important role for LAG-3 immunosuppression during progression of sepsis." (PMID 33613563, 2020). "Importantly, anti-LAG-3 antibody was administered in a therapeutic manner at 3 h after sepsis induction, which increases the clinical relevance." (PMID 33613563, 2020). "In this study, we found that PD-1 and LAG3 have unique expression characteristics in sepsis." (PMID 31440257, 2019). "Given the changes in LAG3 and PD-1, we need to closely examine their specific roles in sepsis." (PMID 31440257, 2019). "Furthermore, we also found that the absolute number of lymphocytes in the patients with sepsis was negatively correlated with the proportion of LAG3 and PD-1 double-positive T cells (r = −0.653, 95%CI: −0.831 to −0.356, P = 0.0003)." (PMID 31440257, 2019). "Therefore, the clinical relevance of LAG3 overexpression during sepsis in HIV positive patients appears limited." (PMID 26871709, 2016). "Hypothetically, increased expression of LAG3 could be a disadvantage in HIV positive sepsis patients by inhibiting an effective T-cell response." (PMID 26871709, 2016). "Previous studies have found that co-inhibitory molecules, such as PD-1, CTLA-4, LAG-3, VISTA, are upregulated during sepsis, we then queried the expression of TIGIT and its ligand CD155 upon sepsis insult." (PMID 38545097, 2024). "Several checkpoint receptors including programmed cell death protein 1 (PD-1), B and T lymphocyte attenuator (BTLA), and lymphocyte activation gene 3 (LAG-3), along with their respective ligands such as PD-L1, are upregulated on leukocytes during sepsis." (PMID 38057824, 2023). "We suppose that altered expression levels of LAG-3 and/or impaired protein function are the rationale behind our finding of advantages of the LAG-3 rs951818 AA-genotype in sepsis survival." (PMID 34830585, 2021).
Sepsis (continued). "The present study was conducted to evaluate the potential influence of genetic variations in the lymphocyte-activation gene 3 (LAG-3) on outcome and disease progression in a representative cohort of patients with sepsis." (PMID 34830585, 2021). "Double LAG-3 and PD-1 positive T cells show significant dysfunction and LAG-3 is upregulated later in the course of sepsis progression in patients." (PMID 33613563, 2020). "Expressions of CD40, CD86, PD-1, PD-L1, TIM-3 and LAG-3 were not changed on B220+ lymphocytes after sepsis." (PMID 40155394, 2025). "Immunomodulatory cytokines (IFN-γ, IL-7, -15, -33), growth factors (GM-CSF), thymosin-α, immune checkpoint inhibitors (PD-1/PD-1L, CTLA-4, LAG-3, TIM-1), administration of immunoglobulins, and cell therapy with mesenchymal cells are being studied for use in patients with sepsis." (PMID 40566028, 2025). "Besides PD-1, the expression of other inhibitory receptors such as LAG-3 and 2B4 on CD8+ T cells in sepsis is also significantly increased; their binding with respective ligands synergistically enhances the inhibition of T cell function." (PMID 41462924, 2025). "CD8+ T cells from sepsis patients significantly upregulate the expression of multiple inhibitory receptors, including Programmed Death-1 (PD-1), T cell Immunoglobulin and Mucin-domain Containing-3 (TIM-3), and Lymphocyte Activation Gene-3 (LAG-3)." (PMID 41462924, 2025). "Our current study shows that the inhibitory function of sepsis-induced PCs towards T cells is not mediated through increased LAG-3 expression but involves activation of the PD-1 pathway." (PMID 40155394, 2025). "In addition to the PD-1/PD-L1 recognition system, other immune checkpoints, such as cytotoxic T lymphocyte antigen-4 (CTLA-4), T cell membrane protein-3 (TIM-3), lymphocyte activation-gene-3 (LAG-3) and 2B4, are upregulated during the course of sepsis." (PMID 34400893, 2021). "This study examined the effect of the rs951818 SNP of the negative costimulatory lymphocyte-activation gene 3 (LAG-3) on sepsis mortality and disease severity." (PMID 34830585, 2021). "The change in receptor expression pattern that we observed over the course of sepsis, increased TIM-3, LAG-3 and CD69 with decreased IL-7R expression, is consistent with the phenotype of immune cell exhaustion, although the functional impairment was not as severe." (PMID 22742734, 2012). "Recently, the potential relationship between PD-1 and LAG3 was reported in other non-septic diseases, and moreover, LAG3 activation can resist the therapeutic effect of PD-1 blockade, but their role in sepsis is still unclear." (PMID 31440257, 2019). "During the acute phase of sepsis (i.e., the first seven days in patients), lymphocytes—T cells in particular—upregulate the inhibitory receptors cytotoxic T lymphocyte antigen-4 (CTLA4), T cell immunoglobulin mucin-3 (TIM-3), lymphocyte activation gene 3 (LAG-3), or interleukin-7 (IL-7) receptor." (PMID 30871101, 2019). "Hence, downregulation of LAG3 in HIV negative sepsis patients may be an adequate response to boost the immune system." (PMID 26871709, 2016). "Sepsis patients tended to have a slightly higher frequency of CD38+, CD69+ and lymphocyte activation gene 3 (LAG‐3)+ MAIT cells compared with non‐sepsis patients, although not significantly so." (PMID 40041474, 2025). "First, biomarkers of T-cell activation and IFNγ-activity (e.g. GZMB, PDL1, LAG3, CXCL9) were present broadly in IHF, including hyperferritinemic sepsis, and were not unique to one diagnosis (PC1)." (PMID 39264477, 2024). "Lymphocyte activation-gene-3 (LAG-3) as well as T cell immunoglobulin and mucin-domain containing-3 (TIM-3) were elevated on T cells and TIM-3 also on monocytes in sepsis but not in severe sepsis and septic shock." (PMID 38187375, 2023).
Sepsis (continued). "Principal component analysis of GZMA, GZMB, CD8A, CD8B, KLRD1, PRF1 and LAG3 gene expression revealed 81% explained variance for the first principal component considering HIV negative and HIV positive sepsis patients." (PMID 26871709, 2016). "HIV positive sepsis patients in both ICU cohorts showed overexpression of genes involved in granzyme signaling (GZMA, GZMB), cytotoxic T-cell signaling (CD8A, CD8B) and T-cell inhibitory signaling (LAG3), compared to HIV negative patients." (PMID 26871709, 2016).
head and neck squamous cell carcinoma (29 papers, 2018 to 2025). A squamous cell carcinoma that arises from any of the following anatomic sites: lip and oral cavity, nasal cavity, paranasal sinuses, pharynx, larynx, and salivary glands. "Antibodies blocking LAG-3 have been shown to promote antitumor immune response in head and neck squamous cell carcinoma (HNSCC)." (PMID 41194225, 2025). "In head and neck squamous cell carcinoma, LAG-3 was upregulated on tumor-infiltrating T cells and correlated with reduced OS." (PMID 33803936, 2021). "Several ongoing trials targeting LAG-3 are at range for different cancer types, including head and neck squamous cell carcinoma (NCT03625323)." (PMID 33396515, 2020). "Moreover, transfection of miR-21-5p has also been reported to significantly elevate the expression levels of CTLA-4 and LAG3 miRNA in head and neck squamous cell carcinoma." (PMID 36765782, 2023). "In addition, LAG-3 expression closely correlated with CD163 in primary head and neck squamous cell carcinoma." (PMID 32756500, 2020). "In head and neck squamous cell carcinoma (HNSCC), microRNA (miR)-7704 and miR-21-5p were shown to have the capability to increase the expression of LAG-3." (PMID 39796650, 2024). "More recently, a study performed in patients with head and neck squamous cell carcinoma and NSCLC showed [89Zr]-BI 754111, a LAG-3 targeting mAb, to be a predictive imaging biomarker for anti-LAG-3 therapy." (PMID 37841258, 2023). "In human primary head and neck squamous cell carcinoma (HNSCC), overexpression of LAG-3 on tumor infiltrating lymphocytes correlates with high pathological grade, larger tumor size and positive lymph node status." (PMID 36077354, 2022). "Moreover, LAG3 and ADAM10 expression was assessed to understand the translational relevance of LAG3 shedding in a cohort of patients with head and neck squamous cell carcinoma (HNSCC)." (PMID 30400822, 2018).
multiple myeloma (29 papers, 2015 to 2025). "In contrast, LAG3 rs870849 was prevalent at elevated allele frequencies in myeloma patients, with allele frequency 0.61 in male and 0.53 in female patients compared to 0.39 in the European population." (PMID 41614836, 2025). "For example, SNPs in the intron region of LAG3 (rs2365094 and rs3782735) have been found to be significantly associated with susceptibility to multiple myelomas." (PMID 35265454, 2022). "LAG3 rs870849 on 12p13 may be a significant male-predominant myeloma risk allele, possibly with a bias toward light chain myeloma with renal dysfunction." (PMID 41614836, 2025). "In all genetic models LAG3 rs870849 was significantly associated with risk for multiple myeloma." (PMID 41614836, 2025). "Similarly, decreased LAG3 expression on CD4+Foxp3+ T cells was associated with significantly longer PFS in patients with multiple myeloma." (PMID 39456740, 2024). "In preclinical models, LAG3 blockade restores T cell cytotoxicity and enhances anti-myeloma responses, particularly when combined with PD-1 inhibition." (PMID 41614836, 2025). "Here, we analyzed the prevalence of the common LAG3 gene variant rs870849 and the common CTLA4 gene variant rs231775 in myeloma patients eligible for autologous stem cell transplantation." (PMID 41614836, 2025). "To investigate if multiple myeloma cells engage TIM-3-, LAG-3- and 2B4-mediated pathways, we analyzed the expression of IR ligands in two multiple myeloma cell lines (U266 and MM1.s) in both resting conditions and in pro-inflammatory conditions." (PMID 38510235, 2024). "Purified Cluster of Differentiation 138 (CD138+) PCs from patients with premalignant conditions, active multiple myeloma (MM), and controls were analyzed for the expression of LAG-3 by flow cytometry." (PMID 38203720, 2023). "Micro-environmental cells that express LAG-3 were found to be increased during the progression of smoldering multiple myeloma (SMM)." (PMID 38203720, 2023). "LAG-3 mAb as monotherapy is also being investigated in esophageal or gastric cancer, multiple myeloma, and chordoma." (PMID 36135216, 2022). "Trends toward higher double positivity were noted, only achieving significance for PD-1+LAG3+ cells (46.57 ± 5.1%) in late relapsed multiple myeloma compared with HD CAR T cells (26.0 ± 4.2%, P < 0.05)." (PMID 36874402, 2022). "Another phase I/II randomized trial tested the efficacy of anti-TIGIT and anti-LAG3 mAbs in patients with relapsed refractory multiple myeloma either alone or in combination with pomalidomide and dexamethasone (NCT04150965, NCT02913313)." (PMID 36135216, 2022). "PD-1+LAG3+ double positive cells were also present in significantly higher numbers in late relapsed multiple myeloma-derived CAR T cells compared with HD-derived CAR T cells." (PMID 36874402, 2022). "Temporal phenotypic analysis of bone marrow from myeloma-bearing mice demonstrated that elevated percentages of PD-1, 2B4, LAG-3 and TIM-3 proteins were expressed on T cells." (PMID 25614821, 2015). "Similar to the increase in PD-1 expression, increasing percentages of T cells in the bone marrow expressed TIM-3, LAG-3 and 2B4 as myeloma burden progressed." (PMID 25614821, 2015). "The current study furthers the earlier work by demonstrating that myeloma experienced T cells upregulate expression of multiple checkpoint receptors including PD-1, LAG-3, TIM-3 and 2B4." (PMID 25614821, 2015). "Myeloma-bearing mice were treated with a low dose of whole body irradiation and combinations of blocking antibodies to PD-L1, LAG-3, TIM-3, CD48 (the ligand for 2B4) and CTLA4." (PMID 25614821, 2015). "LAG3 rs870849 may affect survival and treatment outcome after autologous stem cell transplantation in myeloma patients with favorable outcomes in rs870849 carriers." (PMID 41614836, 2025). "In the promotion of myeloma development, LAG3 rs870849 may increase the number of exhausted T cells with concomitant loss of immune surveillance." (PMID 41614836, 2025).